FBXW7 (F-box and WD repeat domain containing 7)
Description:
Substrate recognition component of a SCF (SKP1-CUL1-F-box protein) E3 ubiquitin-protein ligase complex which mediates the ubiquitination and subsequent proteasomal degradation of target proteins. Recognizes and binds phosphorylated sites/phosphodegrons within target proteins and thereafter brings them to the SCF complex for ubiquitination. Identified substrates include cyclin-E (CCNE1 or CCNE2), DISC1, JUN, MYC, NOTCH1 released notch intracellular domain (NICD), NFE2L1, NOTCH2, MCL1, MLST8, RICTOR, and probably PSEN1. Acts as a negative regulator of JNK signaling by binding to phosphorylated JUN and promoting its ubiquitination and subsequent degradation. Involved in bone homeostasis and negative regulation of osteoclast differentiation. Regulates the amplitude of the cyclic expression of hepatic core clock genes and genes involved in lipid and glucose metabolism via ubiquitination and proteasomal degradation of their transcriptional repressor NR1D1; CDK1-dependent phosphorylation of NR1D1 is necessary for SCF(FBXW7)-mediated ubiquitination. Also able to promote 'Lys-63'-linked ubiquitination in response to DNA damage. The SCF(FBXW7) complex facilitates double-strand break repair following phosphorylation by ATM: phosphorylation promotes localization to sites of double-strand breaks and 'Lys-63'-linked ubiquitination of phosphorylated XRCC4, enhancing DNA non-homologous end joining.
Synonyms: hAgo; FBW7; FBX30; SEL10; AGO; FLJ11071; SEL-10; CDC4; FBXW6; DEDHIL; FBW6; hCdc4
Tractability: Small molecule: a structure with a bound ligand is known; it has a binding pocket of medium quality. PROTAC: UniProt records ubiquitination sites on it; ubiquitination databases record sites on it.
Gene: Protein-coding gene on chromosome 4 (152,320,544 to 152,536,107, reverse strand). Ensembl gene ENSG00000109670.
Subcellular location: Nucleus, nucleoplasm (Isoform 1); Chromosome; Cytoplasm (Isoform 2); Nucleus, nucleolus (Isoform 3)
Subcellular location (Human Protein Atlas): Nucleoplasm; Vesicles
Pathways (Reactome):
Disease: Constitutive Signaling by NOTCH1 HD+PEST Domain Mutants; Constitutive Signaling by NOTCH1 PEST Domain Mutants; Loss of Function of FBXW7 in Cancer and NOTCH1 Signaling
Metabolism of proteins: Association of TriC/CCT with target proteins during biosynthesis; Neddylation
Signal Transduction: NOTCH1 Intracellular Domain Regulates Transcription; Negative regulation of NOTCH4 signaling
Immune System: Antigen processing: Ubiquitination & Proteasome degradation
Gene Ontology:
Molecular function: cyclin binding; identical protein binding; phosphothreonine residue binding; protein binding; protein-macromolecule adaptor activity; ubiquitin protein ligase binding; ubiquitin-like ligase-substrate adaptor activity; ubiquitin-protein transferase activator activity; ubiquitin binding
Biological process: negative regulation of gene expression; negative regulation of osteoclast development; positive regulation of establishment of protein localization to mitochondrion; positive regulation of oxidative stress-induced neuron intrinsic apoptotic signaling pathway; positive regulation of proteasomal protein catabolic process; positive regulation of protein ubiquitination; positive regulation of ubiquitin-dependent protein catabolic process; proteasome-mediated ubiquitin-dependent protein catabolic process; protein ubiquitination; regulation of circadian rhythm; regulation of mitophagy; SCF-dependent proteasomal ubiquitin-dependent protein catabolic process; sister chromatid cohesion; lipid homeostasis; negative regulation of hepatocyte proliferation; negative regulation of Notch signaling pathway; negative regulation of SREBP signaling pathway; negative regulation of triglyceride biosynthetic process; positive regulation of epidermal growth factor receptor signaling pathway; positive regulation of ERK1 and ERK2 cascade; protein stabilization; regulation of cell cycle G1/S phase transition; regulation of lipid storage; regulation of mitotic cell cycle; regulation of protein localization; and 3 more
Cellular component: chromosome; cytoplasm; nucleoplasm; nucleus; Parkin-FBXW7-Cul1 ubiquitin ligase complex; SCF ubiquitin ligase complex; cytosol; nucleolus
Genetic constraint (gnomAD): Loss-of-function variants: 7 observed, 72.45 expected, observed/expected ratio (o/e) 0.0966, 90% interval 0.054 to 0.18. The upper end of that interval is the gene's LOEUF score, 0.18, which puts it in group 1 of 6, group 1 being the genes least tolerant of losing a copy. Missense variants: 441 observed, 790.11 expected, observed/expected ratio (o/e) 0.56, 90% interval 0.51 to 0.6. Synonymous variants: 281 observed, 280.05 expected, observed/expected ratio (o/e) 1, 90% interval 0.91 to 1.11.
Cancer hallmarks: genome instability and mutations (suppresses)
Homologues: Orthologues: chimpanzee FBXW7 (100% identical), macaque FBXW7 (99% identical), dog FBXW7 (99% identical), pig FBXW7 (98% identical), guinea pig FBXW7 (97% identical), rat Fbxw7 (96% identical), rabbit FBXW7 (94% identical), tropical clawed frog fbxw7 (88% identical), mouse Fbxw7 (78% identical), zebrafish fbxw7 (72% identical), Drosophila melanogaster ago (61% identical), tropical clawed frog XB5721468 (26% identical), and 1 more. Paralogues in human: TRAF7 (18% identical), BTRC (18% identical), FBXW11 (18% identical), WDR49 (17% identical), EFCAB8 (16% identical), WDR86 (15% identical), WDR64 (14% identical), FBXW9 (14% identical), FBXW8 (10% identical), PAAF1 (9% identical), FBXW12 (8% identical), WDR54 (8% identical), and 2 more.
Diseases named in the same sentence as FBXW7 in open-access papers:
FBXW7 is named in the same sentence as 270 diseases in open-access papers, as found by Europe PMC text mining. Sharing a sentence is not in itself a finding about the gene and the disease. The quoted sentences say what the papers report.
breast cancer (103 papers, 2010 to 2025). A primary or metastatic malignant neoplasm involving the breast. "Reduced FBXW7 expression leads to abnormal stabilization of its substrates, and mutations or deletions in the FBXW7 gene have been linked to breast cancer progression and chemoresistance." (PMID 39445291, 2024). "FBXW7 is a tumor suppressor, and mutations in this gene can lead to a variety of cancers such as leukemia, breast cancer, gastric cancer, colon cancer, and nephroblastoma." (PMID 39364007, 2024). "In this study, multiple candidate genes, especially FBXW7, were identified as possibly being associated with the racial disparity of breast cancer between African American and Caucasian patients." (PMID 39445291, 2024). "Breast cancer development is affected by associated regulators, FBXW7, and protein substrates crosstalk at the molecular level." (PMID 37658431, 2023). "FBXW7 LOF in several human cancers has multiple clinical implications, including prognostic value; for instance, rapamycin has been proven to inhibit FBXW7-deficient breast cancer cells by mTOR inhibition." (PMID 36901733, 2023). "Through facilitating the ubiquitination and destruction of cell cycle-relevant molecules, FBXW7 has been implicated in the modulation of the cell cycle process in breast cancer." (PMID 37658431, 2023). "Low levels of FBXW7 cause abnormal stability of pertinent substrates, mutations and/or deletions in the FBXW7 gene have been reported to correlate with breast cancer malignant progression and chemoresistance." (PMID 37658431, 2023). "SRY-related HMG-box 4 (SOX4) binding to the FBXW7 promoter upregulates FBXW7 expression in ER + breast cancers, causing enhanced turnover of GATA-binding protein 3 (GATA3), and thus promoting tamoxifen tolerance." (PMID 37658431, 2023). "miR-182 has also been associated with the progression of glioma and breast cancers by directly targeting FBXW7; again highlighting the broad role indiviudal miRNAs play in regulating FBXW7 across various cancers." (PMID 35346215, 2022). "FBXW7 mutations and deletions can cause the accumulation of these genes related to cancer cell proliferation and have been found in ovarian cancer, breast cancer, and colorectal cancer." (PMID 36304995, 2022). "Most substrates regulated by FBXW7 are oncoproteins, and a high mutational rate of FBXW7 has been frequently found in many cancer types, including lung, colorectal, and breast cancers." (PMID 36104351, 2022). "This subclone also contained mutations in PTEN and FBXW7, both tumor suppressor genes previously reported as driver genes for breast cancer." (PMID 34075047, 2021). "For example, circFBXW7 inhibits tumor growth and metastasis in glioma and breast cancer by encoding a 21kDa novel protein FBXW7-185aa and blocking miR-197-3p." (PMID 32194644, 2020). "FAM83D-mediated FBXW7 down-regulation is associated with an increase in the expression of FBXW7 substrates, such as c-Myc, mTOR and c-Jun, in breast cancer; and FAM83D is frequently deregulated in breast and colon cancer." (PMID 30086763, 2018). "Deletions and mutations of FBXW7 have been identified in a variety of cancers including colorectal cancer, gastric cancer, ovarian cancer, neuroglioma and breast cancer." (PMID 28149200, 2017). "The blood level of FBXW7 expression has also been associated with the prognosis of breast cancer patients." (PMID 27417709, 2016). "Diagnostic biopsies of breast cancer patients were analyzed by immunohistochemistry for the expression of FBXW7, MCL1 and PLK1." (PMID 27409838, 2016). "Loss of expression of FBXW7 has been reported in a series of breast carcinomas where Cyclin E was upregulated and associated with poor prognosis but its relationship with other substrates has not been addressed." (PMID 27409838, 2016).
breast cancer (continued). "FBXW7 is a bona fide tumor suppressor that is inactivated by gene mutation or expression downregulation in numerous human malignancies, including breast cancer." (PMID 24344117, 2013). "The Fbxw7/hCdc4 isoform responsible for mTor degradation was not defined in this study, but it's noteworthy that mTor localizes to the cytosol and that breast cancer cells with loss of Fbxw7/hCdc4 were shown to be more sensitive to mTor inhibitors." (PMID 21122106, 2010). "This study provides new insights into the causes and consequences of FBXW7/hCDC4 inactivation in breast cancer." (PMID 21122106, 2010). "Therefore, when both mutations and gene expression are considered, gene FBXW7 is the gene that is most likely associated with the racial disparity in breast cancer." (PMID 39445291, 2024). "Low FBXW7 expression is linked to breast cancer malignancy, therefore considering restoring its suppressive function and designing potential FBXW7 inducers may be a viable therapeutic strategy." (PMID 37658431, 2023). "FBXW7 strictly controls the ubiquitination and degradation of proliferation-associated binding proteins, and its expression profile with substrates governs breast cancer cell proliferation and apoptosis." (PMID 37658431, 2023). "Multiple reports have confirmed that FBXW7 is closely linked to drug resistance in breast cancer." (PMID 37658431, 2023). "This indicates that in FBXW7-deficient breast cancers, the NF-κB signaling pathway that should be subject to normal E3 ubiquitin ligase binding and degradation is blocked, leading to increased NF-κB DNA binding activity and promoting tumor growth and metastasis." (PMID 37658431, 2023). "PKC inhibitor J-4 and PLK1/2 inhibitor onvansertib are in preclinical and clinical trials, respectively, and by inhibiting these molecules, endogenous FBXW7 expression may be restored and promote the turnover of breast cancer-associated oncogenic proteins." (PMID 37658431, 2023). "Moreover, GSK3β-mediated CPD phosphorylation of FBXW7 is critical for breast cancer proliferation-associated substrate recruitment." (PMID 37658431, 2023). "Mutations in FBXW7 are relatively rare in breast cancer patients." (PMID 30086763, 2018). "For example, it has been reported that the inactivation of FBXW7 can be associated with favorable prognosis in a subset of breast cancers, suggesting that the physiological role of FBXW7 and consequences of its loss may be dependent on cell types and contexts." (PMID 25669969, 2015). "FBXW7/hCDC4 mutations were first identified in breast cancer and ovarian cell lines." (PMID 21122106, 2010). "Although such comprehensive approaches extend beyond the present work, our current findings establish a solid foundation—particularly the FBXW7-mediated axis—for subsequent high-resolution studies into the miR-32-5p/c-MYC regulatory network in breast cancer." (PMID 40711670, 2025). "Unlike colorectal cancer, where miR-32-5p directly targets PTEN/BMP5 to drive metastasis, our work reveals a breast cancer-specific mechanism: miR-32-5p suppresses FBXW7, stabilizing c-MYC." (PMID 40711670, 2025). "Fbxw7 is highly expressed in dormant breast cancer cells; its knockdown reactivates dormant cells, and combining Fbxw7 knockdown with cytotoxic therapy reduces DCC burden." (PMID 41020040, 2025). "The tumor suppressor FBXW7 also hinders breast cancer proliferation and promotes apoptosis by degrading MTDH." (PMID 38977630, 2024). "Identifying the gene FBXW7, among other candidate genes, as a possible contributor to the breast cancer racial disparity is important because it leads to a greater understanding of the processes involved in the pathogenesis of breast cancer." (PMID 39445291, 2024).
breast cancer (continued). "This demonstrates that FBXW7 slows the advancement of breast cancer by abating the number of immune cells involved in immune evasion and present in TME." (PMID 37658431, 2023). "Low FBXW7 expression in breast cancer deregulates cyclin E and D1, promoting aberrant cell division and G1/S phase transition." (PMID 37658431, 2023). "Taken together, various signaling pathways and gene crossing are involved in the process FBXW7 controls breast cancer proliferation, cell cycle, and metastasis." (PMID 37658431, 2023). "Recent evidence has connected abnormal FBXW7 expression to breast cancer growth, metastasis, and drug resistance." (PMID 37658431, 2023). "Anti-miR-223-3p upregulates FBXW7 translationally, which suppresses EMT, breast cancer cell migration, and invasiveness, but information on the specific targets of FBXW7 remains to be investigated." (PMID 37658431, 2023). "In this review, we highlight the functional role of FBXW7 in the spectrum of malignant behaviors in breast cancer, ubiquitination targets, and the mechanisms of FBXW7 expression." (PMID 37658431, 2023). "MiR-223-3p partially plays its carcinogenic role by reducing the expression of FBXW7, thereby promoting the invasion and metastasis of breast cancer cells." (PMID 36998461, 2023). "In breast cancer cells, miR-32 induces cell proliferation and migration, evading apoptosis by down-regulating FBXW7." (PMID 37047300, 2023). "To further understand the impact of FBXW7 mutations on breast cancer biology, we performed a GSEA using RNA-seq data and KEGG pathway annotation for the contrast FBXW7-mutant versus wild-type tumors." (PMID 37902422, 2023). "As a result, further technological advancements in the field of genomics and increased research on the complex role of FBXW7 in chemoresistance are required to target FBXW7 in breast cancer therapy." (PMID 37658431, 2023). "NF-κB, as a pro-inflammatory factor, also mediates the regulation of intrinsic and adaptive immune functions, and FBXW7 can regulate breast cancer through interaction with the pathway." (PMID 37658431, 2023). "It is meaningful to take into account the potential therapeutic strategies of reducing breast cancer angiogenesis by targeting FBXW7 and its downstream proteins in light of the critical function that FBXW7 plays in modulating angiogenesis." (PMID 37658431, 2023). "Crosstalk between FBXW7 and related binding proteins regulates immune cell numbers, metastasis, and the premetastatic niche, playing a role in breast cancer immunosuppression." (PMID 37658431, 2023). "Further research on FBXW7's biological and molecular mechanisms in breast cancer will improve present therapy options and benefit more advanced breast cancer patients." (PMID 37658431, 2023). "Some FBXW7 regulators include miRNAs, such as miR-27 in lung cancer, miR-32 in breast cancer, miR-92a in cervical cancer, miR-223 in gastric cancer, miR-182 in lung cancer, and miR-223 in T-cell lymphoma." (PMID 37047300, 2023). "In summary, through regulating multiple intricate signaling pathways and targets, FBXW7 has a significant impact on the development of breast cancer." (PMID 37658431, 2023). "Kaplan–Meier OS analysis of breast cancer patients revealed that low expression of FBXW7, SRGAP2, MTMR3 as well as CDC42, the partner of CDC42BPA, is associated with poor prognosis." (PMID 37463901, 2023). "As ubiquitinated proteins are mainly degraded by the proteasome pathway, and interestingly, it was reported that AEG-1 can be ubiquitinated by FBXW7 (an E3 ubiquitin ligase) in breast cancer cells." (PMID 36276642, 2022). "High levels of miR-32 expression downregulate FBXW7, promote cell proliferation, migration and suppress apoptosis in breast cancer." (PMID 35346215, 2022). "FBXW7 was expressed at a low level in breast cancer tissues and cell lines and rescuing FBXW7 would at least partly reverse the oncogenic effect of miR-27a." (PMID 34299149, 2021).